RN7SKP82 (RN7SK pseudogene 82)
Gene: Miscellaneous RNA gene on chromosome 4 (42,892,396 to 42,892,618, forward strand). Ensembl gene ENSG00000252595.
Homologues: Orthologues: mouse Gm54993 (52% identical), guinea pig 7SK (43% identical). Paralogues in human: RN7SKP206 (63% identical), RN7SKP240 (63% identical), RN7SKP37 (63% identical), RN7SKP118 (63% identical), RN7SKP185 (63% identical), RN7SKP65 (63% identical), RN7SKP187 (62% identical), RN7SKP25 (62% identical), 7SK (62% identical), RN7SKP160 (62% identical), RN7SKP193 (62% identical), RN7SKP150 (61% identical), and 284 more.